CHURC1 (churchill domain containing 1)
Description:
Transcriptional activator that mediates FGF signaling during neural development (By similarity). Plays a role in the regulation of cell movement (By similarity). [Isoform 4]: Does not bind DNA by itself.
Synonyms: C14orf52; CHCH; My015; FLJ33064
Tractability: PROTAC: ubiquitination databases record sites on it; its protein half-life has been measured.
Gene: Protein-coding gene on chromosome 14 (64,914,361 to 64,944,591, forward strand). Ensembl gene ENSG00000258289.
Subcellular location (Human Protein Atlas): Cytosol
Gene Ontology:
Molecular function: protein binding; zinc ion binding
Biological process: fibroblast growth factor receptor signaling pathway; positive regulation of DNA-templated transcription
Genetic constraint (gnomAD): Loss-of-function variants: 10 observed, 11.61 expected, observed/expected ratio (o/e) 0.86, 90% interval 0.53 to 1.46. The upper end of that interval is the gene's LOEUF score, 1.46, which puts it in group 6 of 6, group 1 being the genes least tolerant of losing a copy. Missense variants: 111 observed, 111.49 expected, observed/expected ratio (o/e) 1, 90% interval 0.85 to 1.17. Synonymous variants: 34 observed, 38.77 expected, observed/expected ratio (o/e) 0.88, 90% interval 0.67 to 1.17.
Homologues: Orthologues: chimpanzee CHURC1 (99% identical), dog CHURC1 (97% identical), pig CHURC1 (97% identical), mouse Churc1 (96% identical), rat Fntb (77% identical), zebrafish churc1 (71% identical), tropical clawed frog churc1 (68% identical).
Diseases named in the same sentence as CHURC1 in open-access papers:
CHURC1 is named in the same sentence as 7 diseases in open-access papers, as found by Europe PMC text mining. Sharing a sentence is not in itself a finding about the gene and the disease. The quoted sentences say what the papers report.
lung adenocarcinoma (3 papers, 2022 to 2025). A carcinoma that arises from the lung and is characterized by the presence of malignant glandular epithelial cells. "We found a novel apaQTL-SNP, rs10138506, which might affect lung adenocarcinoma (LUAD) risk by modulating the 3′UTR length of CHURC1." (PMID 36358727, 2022).
Obesity (1 paper, 2019). Accumulation of substantial excess body fat. "Churchill domain containing 1 (CHURC1) eQTLs have recently been reported to be associated with T2D and obesity in both adipose and muscle tissues, suggesting a pleiotropic effect of this gene in T2D pathophysiology." (PMID 30956117, 2019).
cancer (2 papers, 2022 to 2025). A tumor composed of atypical neoplastic, often pleomorphic cells that invade other tissues. "CHURC1, a transcriptional activator controlling the fibroblast growth factor, is a cancer susceptibility gene, affecting cell proliferation." (PMID 36358727, 2022). "Our finding that CHURC1-FNTB is differentially expressed in B-ALL is novel, though work has been done to pursue this target as a cancer immunotherapy for a variety of different cancers, including AML." (PMID 41020821, 2025).
infection (1 paper, 2019). The state of being infected such as from the introduction of a foreign agent such as serum, vaccine, antigenic substance or organism. "There were 10 common downregulated transcripts with a further six being unique to the synchronised infection (i.e., Hist4h4, 2900010M23Rik, Churc1, Rps15a, Lgals1, S100a16)." (PMID 31546628, 2019).
tumor (1 paper, 2022). "Based on TCGA database, the CHURC1 expression between LUAD tumor tissues (n = 526) and adjacent non-tumor tissues (n = 108) was significantly different (p < 0.001), and lower CHURC1 expression levels were found in tumor tissues." (PMID 36358727, 2022). "Therefore, CHURC1 may exert tumor-suppressive effects through certain transcription factors (e.g., SIN3A) and further affect LUAD development." (PMID 36358727, 2022). "In our present study, the CHURC1 expression level in LUAD tumor tissues was lower than that in the adjacent non-tumor tissues based on TCGA data, indicating that CHURC1 may function as a tumor-suppressor gene in LUAD development." (PMID 36358727, 2022). "Furthermore, CHURC1 expression levels in 57 LUAD paired samples were also analyzed, and the results showed that CHURC1 expression in LUAD tumor tissues was significantly lower than that in the adjacent non-tumor tissues (p = 0.002)." (PMID 36358727, 2022). "The results show that CHURC1 had no statistically significant expression difference between LUAD tumor tissues and adjacent non-tumor tissues (p = 0.33)." (PMID 36358727, 2022).
CHURC1 also shares sentences with these, for which no sentence is quoted: autism (1 paper); lung carcinoma (1).